STAT3 (signal transducer and activator of transcription 3)
Diseases named in the same sentence as STAT3 in open-access papers (continued):
Sharing a sentence is not in itself a finding about the gene and the disease.
tumor (continued). "STAT3 is commonly constitutively activated in liver and play a key role in tumor formation." (PMID 32322693, 2020). "Besides, we demonstrated that anti-tumor compounds are able to target the STAT3 signaling pathway in suppressing GC proliferation and malignancy." (PMID 32545648, 2020). "STAT3 negatively regulates dendritic cells, effector T cells, natural killer cells, and neutrophils, suggesting that STAT3 activation in immune cells likely leads to the down-regulation of anti-tumor immunity." (PMID 32824865, 2020). "Optimization of STAT3/STAT5 inhibitors by chemical modifications and drug delivery systems are both required for resolving issues linked to stability, cell permeability, and targeted delivery to tumor cells." (PMID 31963765, 2020). "Besides, melanoma TEV have been shown to induce IL-6 production in DC, leading to STAT3-dependent matrix metalloproteinase 9 production by tumor cells, promoting thereby their invasiveness." (PMID 32878277, 2020). "STAT3 silencing mediated by this CpG-siRNA inhibited tumor growth in xenograft models of AML or MM." (PMID 31963765, 2020). "Under oncogenic stress STAT3 exerts its tumor suppressive function by preventing disease initiation, while in the absence of oncogenic stress it acts as an oncogene and facilitates tumor cell proliferation and tumor growth/burden." (PMID 32365499, 2020). "KLF5 might inhibit cell invasion by suppressing the transcription of IGF1 in tumor cells and subsequently inhibiting its downstream activation of STAT3/MMP9." (PMID 32546700, 2020). "In tumor studies, STAT3 regulates PD-L1 expression transcriptionally by binding to its promoter." (PMID 32154274, 2020). "We analyzed the mRNA level of tumor-associated genes such as Cadherin-1, Ki-67, PCNA, β-catenin, STAT3, and COX2, as well as the protein levels of tumor marker VEGF, its downstream transcription activator STAT3 and p-STAT3, and the tumor proliferation marker PCNA." (PMID 32582527, 2020). "Elucidating the role played by STAT1 and STAT3 in the regulation of PD-L1 in HNSCC may shed light on potential therapeutic targets or factors influencing the ability of these tumours to respond to a PD-L1 blockade." (PMID 31853007, 2020). "Furthermore, milk fat globule epidermal growth factor VIII (MFG-E8) in TAMs enhances cisplatin resistance in tumor cells in concert with IL-6 via regulating the signal transducer and activator of transcription-3 (STAT-3) and hedgehog (Hh) signaling." (PMID 32992449, 2020). "Second, STAT3 acts as a transcription factor that activates several downstream target genes that are involved in multiple steps of metastasis, including invasion, cell survival, self-renewal, angiogenesis, and tumor-cell immune evasion." (PMID 33371351, 2020). "We treated tumor-bearing mice with a combination of STAT3 inhibitor and NFκB inhibitor, JSH-23." (PMID 33330068, 2020). "In the Rhabdomyosarcoma (RMS), mutations in FGFR4 tyrosine kinase domain (K535 and E550) might activate STAT3 signaling, increasing tumor growth and metastatic potential in mice model." (PMID 32154250, 2020). "Thus, there are some attempts to combine CAR-T therapy with STAT3 inhibitors for improving the persistence and anti-tumor effects, as well as negating toxicities of CRA-T cells in vivo." (PMID 32972405, 2020). "The ability of B cells to modulate tumor angiogenesis depends on activation of STAT3." (PMID 31690961, 2020). "STAT3 activity is also part of the molecular mechanism leading tolerance toward tumor antigens." (PMID 33330068, 2020). "In addition to the selective regulation of cytokine signalling, the activation of STAT3 in tumor cells was disturbed, and the increase in proinflammatory cytokines such as IL-6 was further prevented." (PMID 33082817, 2020).
tumor (continued). "In vitro and in vivo experiments showed that UICC could facilitate the expression of IL-6 by combining with its promoter and directly interact with the phospho-STAT3 to improve its protein stability, thus promoting tumor growth and metastasis." (PMID 33520725, 2020). "Furthermore, both CD44 and STAT3 have been shown to crosstalk with matrix metalloproteinases, which are important mediators of tumor angiogenesis." (PMID 33335857, 2020). "That led us to test whether STAT3 mediated tumor growth and evasion mechanisms could involve p65-NFκB modulation." (PMID 33330068, 2020). "Autophagy can also reduce immunotherapy effect by impairing cytotoxic T-lymphocyte (CTL)-mediated tumor cell lysis when autophagy is induced under hypoxia conditions, activating STAT3 signaling in target cells which in turn favors tumor cell survival, proliferation, and immune escape." (PMID 33324568, 2020). "Moreover, myotube atrophy induced by HCT116 tumor cells was partially rescued by inhibition of STAT3, further suggesting that STAT3 remains an important player in mediating CRC-induced cachexia." (PMID 31915140, 2020). "Propofol may exert similar inhibitory effect on in vivo tumor metastasis, and this effect was probably due to the reduced expression of STAT3, HOTAIR, and WIF‐1 expression and subsequent activation of Wnt signaling pathway." (PMID 31953926, 2020). "However, prolonged production of IL-10 in the TME is a potent promoter of cancer as it contributes to the constitutive activation of STAT3 in immune cells and tumor cells, thereby restraining the anti-cancer immune responses and driving oncogenic signaling." (PMID 31936322, 2020). "Because STAT3 phosphorylation in CRC cell lines with strong cancer stemness characteristics may respond to regorafenib for tumor survival." (PMID 33023006, 2020). "Signal transducer and activator of transcription 3 (STAT3) is a point of convergence for numerous oncogenic signals that are often constitutively activated in many cancerous or transformed cells and some stromal cells in the tumor microenvironment." (PMID 33053804, 2020). "UTMC with STAT3 decoy-loaded microbubbles significantly decreases human HNSSC tumor progression." (PMID 33206698, 2020). "Apart from tumor cells, STAT3 is also implicated in many other non-malignant cells in the tumor microenvironment." (PMID 32486001, 2020). "Accordingly, genetic inactivation of the signal transducer and activator of transcription 3 (Stat3) in macrophages, leading to the inactivation of anti-inflammatory IL-10 signaling, has resulted in chronic intestinal inflammation and onset of tumor lesions." (PMID 32962159, 2020). "STAT3 is well-known for its roles in tumor initiation and development." (PMID 32733808, 2020). "In a separate analysis, 7.5% of primary RMS contained a tyrosine kinase domain mutation, and the particular mutants K535 and E550 increased tumor proliferation, metastatic potential, autophosphorylation, and Stat3 signaling when expressed in a murine RMS cell line." (PMID 32393201, 2020). "In summary, our findings suggest that RNF180 could reduce tumor metastasis in GC by inhibiting STAT3 activation via RhoC protein degradation through the ubiquitin–proteasome system." (PMID 33082325, 2020). "We detected that MELK overexpression could induce M2 macrophage polarization via the miR-34a/JAK2/STAT3 pathway, contributing to doxorubicin chemoresistance in the tumor microenvironment." (PMID 32391256, 2020). "However, excessive activation of STAT3 in malignant tumors results in inflammation-driven repair that promotes drug resistance or tumor progression 48-51." (PMID 31938049, 2020). "Oncogenetic changes activate transcription factors, such as the nuclear factor-κ-B, signal transducer and activator of transcription-3, and the hypoxia-inducible factor 1α in tumor cells, all of which favor the production of inflammatory mediators, including cytokines and chemokines." (PMID 32321522, 2020).
tumor (continued). "Recently, we demonstrated that the chr8p gene SH2D4A (Src homology 2 domain-containing 4A) exhibits tumor-suppressive functions in vivo and in vitro by inhibiting the Interleukin-6 (IL-6) induced Signal Transducer and Activator of Transcription 3 (STAT3) signaling pathway in HCC5,6." (PMID 33257655, 2020). "Moreover, restrained tumor growth was identified in the nude mice treated with miR cluster MC‐let‐7a‐1 ~ let‐7d mimics or STAT3 siRNA." (PMID 31868319, 2020). "For instance, Stat3 deletion from hematopoietic cells results in increased anti-tumor immunity." (PMID 31947933, 2020). "Notably, activation of STAT3 occurs in cancerous cells and in immune cells, such as tumor-infiltrating MDSCs as shown here." (PMID 33679700, 2020). "Activation of the ERK pathway potentiates the activation of HIF-1α, NF-κB, and STAT-3, and these transcription factors are well known to be involved in the tumor growth and progression through the transcriptional regulation of various inflammatory genes, such as adhesion molecules, MMPs, and VEGF." (PMID 32466580, 2020). "Furthermore, aberrant STAT3 activation is also observed in tumor-interacting immune cells; it can increase the production of diverse immunosuppressive factors and decrease the number of immune activation factors." (PMID 32486001, 2020). "Furthermore, STAT3 inhibition potently recovered the expression and secretion of anti-tumour cytokines, suggesting the recovery of function of CD8+ cytotoxic T cells." (PMID 31913856, 2020). "But our data showed that the Stat3-activated macrophages induced by IL-6 are closer to TAMs at the levels of promoting production of immunosuppressive factors and leading to malignant transformation of tumor cells." (PMID 33288772, 2020). "Moreover, our experimental data shows that inhibition of STAT3 increases anti-tumor immune responses." (PMID 33330068, 2020). "Interestingly, miR-1299 has been reported to be a tumor suppressor that inhibits cell proliferation and STAT3 pathway; whereas miR-767 has been reported to affect the maintenance of normal lung function." (PMID 32629833, 2020). "It is well-established that pro-inflammatory cytokines, such as IL-6 and IL-8, play crucial roles in the generation and maintenance of the stem cell-like fraction in tumor cells through stimulating NF-κB and STAT3 signaling, which promotes therapy resistance, tumor recurrence, and metastasis." (PMID 32244804, 2020). "Additionally, Janus Kinase (JAK)/STAT3 signaling is involved in the differentiation of immature DCs under the stimulation of the tumor microenvironment." (PMID 32486001, 2020). "However, B cells induce protumor effects by activating STAT3, promoting tumor angiogenesis and facilitating tumor progression." (PMID 31991604, 2020). "Regarding the mechanism, we found TLR9 signaling and STAT3 activation in tumor cells." (PMID 32483468, 2020). "Furthermore, multivariate Cox proportional hazards regression test identified high p-STAT3 expression in tumor tissue, advanced TNM staging, PVTT and TACE times as the independent predictive factors." (PMID 31942180, 2020). "STAT3 activation in B cells contributes to tumor progression by enhancing angiogenesis." (PMID 31980946, 2020). "The study further showed that the downregulation of STAT3 signaling could also inhibit tumor growth both in vitro and in vivo." (PMID 32872659, 2020). "Furthermore, immunohistochemical staining also showed that p-STAT5/p-STAT3/p-AKT level were also down-regulated in H53-treated xenograft tumor compared to vehicle or IgG1-treated xenograft tumor." (PMID 33362552, 2020). "By silencing of STAT3, the tumor growth rate was reduced with smaller tumor volume." (PMID 31868319, 2020). "Shp1 might represent an interesting target to modulate oncogenic STAT3 activities and thus inhibit tumor growth, promote apoptosis and prevent chemo- and radio-resistance even in tumors in which it is not mutated." (PMID 32596156, 2020).
tumor (continued). "We have postulated that SLC2A3 might regulate the progression of GC by promoting glycolysis reprogramming, activating the STAT3 signaling pathway, and increasing tumor microenvironment macrophage infiltration and M2 subtype transition." (PMID 33061855, 2020). "In addition to its role in the activation of oncogenic gene expression, STAT3 has also been demonstrated to repress the expression of tumor suppressor genes to encourage the survival of cancer cells." (PMID 31847229, 2019). "Besides the effects in cancer cells, STAT3 signaling has also been reported to inhibit the function of immune cells, resulting in the immune suppressive tumor microenvironment." (PMID 31609088, 2019). "It has been proposed that they act via the expression of the transcription factor STAT3, whereby they produce cytokines to promote a tumor-supportive environment by suppressing the proliferation of anti-tumor CD4+ and CD8+ T cells and promoting the activity of regulatory CD4+ T cells." (PMID 31815646, 2019). "Furthermore, LPAR6 mediated HCC tumorigenicity in tumor xenografts, probably through a STAT3/pim-3-dependent mechanism." (PMID 31652837, 2019). "Sesquiterpene lactones, which are enriched in the hexane fraction from Inula helenium L. have been shown to suppress tumor growth in vitro and in vivo by inhibiting STAT3 phosphorylation and decreasing the expression of the downstream target genes, including cyclin D1, c-Myc, and Bcl-2." (PMID 31088482, 2019). "Targeting JAK/STAT3 signaling inhibits tumor growth and enhances antitumor immune responses." (PMID 31861597, 2019). "Our findings suggest that nevirapine significantly repressed migration and invasion/metastasis in WRO 82‐1 cells and tumor xenografts, which may be related to inhibition of IL‐6/STAT3 signaling pathway." (PMID 31631580, 2019). "Several previous studies showed that STAT3 expression enhanced tumor angiogenesis." (PMID 31355138, 2019). "The identification of tumor‐specific STAT3 cofactors may facilitate the development of compounds that interfere exclusively with STAT3 activity in cancer cells." (PMID 31361391, 2019). "Our evidence for EGFR feedback activation in MG63 and U2OS cells post-LY5 treatment may explain the limited repression of tumor growth upon STAT3 dephosphorylation." (PMID 31422383, 2019). "While the classic model of mo-MDSCs expansion only demonstrates that STAT3 regulates mo-MDSCs expansion, we have further verified that GMPs are the critical myeloid progenitor cells, of which STAT3 activity was increased during tumor-bearing conditions." (PMID 31395859, 2019). "It is well-known that the IL-6/STAT3/VEGFA axis plays a key role in tumor angiogenesis." (PMID 30886152, 2019). "We observed similar effects of DFTD tumor cell-specific killing with both STAT3 inhibitors." (PMID 30645971, 2019). "This study revealed the effect of gigantol of PI3K/AKT and JAK/STAT3 suppression on the tumor initiation, growth, and maintenance based on the concept that the cells at the first step of tumor initiation had lesser CSC property than the control untreated cells." (PMID 31861050, 2019). "A recent study revealed that lncRNA TSLNC8 (also known as LINC00589) exerts its tumor suppressive activity through the inactivation of the IL-6/STAT3 signaling pathway via physically interacting with TKT and STAT3, and thus inhibiting STAT3 phosphorylation and transcriptional activity in HCC." (PMID 31906046, 2019). "Thus, active STAT3 in CD4+ T cells generates an inflammatory environment around the budding tumor aids its growth by stimulating angiogenesis and abrogates antitumor response." (PMID 31861720, 2019). "Notably, IL-6-IL-6R interaction not only promotes VEGF-A secretion from classical monocytes but also activates the STAT3 signaling pathway in cancer cells, which enhances tumor cell proliferation in pancreatic ductal adenocarcinoma (PDAC)." (PMID 31474975, 2019).
tumor (continued). "Multiple compelling studies suggest that aberrant signal transducer and activator of transcription 3 (STAT3) signaling plays a key role in facilitating tumor escape from immune detection by impairing antigen presentation and reducing production of immunostimulatory molecules." (PMID 31611880, 2019). "We subsequently generated orthotopic xenografts to evaluate tumorigenicity using these same pretreated GPC lines where, as expected, dual inhibition of STAT3 and IGF-1R conferred the greatest survival benefit and extended tumor latency in the STAT3-low group of mice." (PMID 31399589, 2019). "In this review we will focus on the role of STAT3 and its regulation, e.g., by phosphorylation or acetylation in immune cells and how it might impact immune cell function and tumor progression." (PMID 31480382, 2019). "The sustained activation of STAT3 can induce a large amount of VEGF secretion from tumor cells and then bind to endothelial cell surface receptors to induce proliferation and activation of endothelial cells, thereby, promoting tumor angiogenesis and invasion and metastasis." (PMID 31885639, 2019). "Despite these considerations, even the somewhat limited perfusion of Stat3-siRNA observed in our in vivo experiments with LPP therapy allowed to achieve impressive effects on tumor growth and overall survival, further supporting the suitability of STAT3 as an excellent target for GBM therapy." (PMID 30857197, 2019). "Moreover, crosstalk between TAM and tumor infiltrating cells through STAT3 can improve chemotherapeutic efficacy by repressing antitumoral CD8+ T-lymphocyte activity." (PMID 31885581, 2019). "Interestingly, the authors reported that PTEN null mice developed a tumor-senescent phenotype, associated with a massive secretion of immunosuppressive cytokines, as a consequence of the activation of JAK2/STAT3 pathway in cancer cells." (PMID 31500143, 2019). "Additionally, STAT3 activity decreases the migration of various immune cells to the tumor microenvironment, including NK cells, T cells, neutrophils, and macrophages, further contributing to an immunosuppressive tumor microenvironment." (PMID 31658669, 2019). "This decrease in tumor development was paralleled by a marked reduction of STAT3 phosphorylation." (PMID 31694340, 2019). "Lastly, here we demonstrated that sorafenib and regorafenib do not alter STAT3 phosphorylation in either skeletal or cardiac muscle, despite the fact that minimal changes in phospho-STAT3 were previously observed in the heart following administration of sorafenib or in tumor hosts." (PMID 31018508, 2019). "Importantly, we developed a novel framework that is based on TF target gene expression to distinguish between environmental- and tumor-specific STAT3 activities in gene expression studies." (PMID 31796877, 2019). "Interestingly, we further observed that SG-1721 substantially suppressed STAT3 phosphorylation, proliferation marker Ki-67, and increased cleaved caspase-3 levels in tumor tissues, thus depicting the potent anticancer effects of SG-1721 in vivo." (PMID 31058868, 2019). "However, deletion of Stat3 in the myeloid compartment also reduces RelA acetylation in tumor cells, signifying the importance of the initial cytokine network to maintain constitutive RelA activity." (PMID 31277415, 2019). "Inhibiting the ERK1/2/STAT3 axis reduces Treg cells expansion and re-instates a correct proliferation of effector TILs, turning an immune-suppressive/pro-tumor environment into an immune-active/anti-tumor one." (PMID 31117237, 2019). "Besides acting as an oncogene in a cell autonomous manner, activation of STAT3 in the tumor microenvironment contributes to metastasis, angiogenesis, cancer stem cell maintenance, and immune evasion." (PMID 31752278, 2019).